CDK12 (cyclin dependent kinase 12)
Diseases named in the same sentence as CDK12 in open-access papers (continued):
Sharing a sentence is not in itself a finding about the gene and the disease.
tumor (continued). "Additionally, while CDK12 is highly correlated with the tumour immune microenvironment and response to immunotherapy, its underlying mechanisms remain largely unexplored." (PMID 38503865, 2024). "This also indicates that CDK12 may have a potential regulatory role in the metabolism of tumour cells." (PMID 38736108, 2024). "Furthermore, we conducted immunoassays to explore the exact mechanisms underlying CDK12-induced carcinogenesis, which revealed that increased expression of CDK12 allowed tumours to evade immune surveillance and upregulate immune checkpoint genes." (PMID 38503865, 2024). "Despite its tumor suppressor function, CDK12 has also been found to promote cell proliferation." (PMID 39368479, 2024). "Conversely, CDK12 expression levels decreased with tumour progression in KICH and THCA." (PMID 38503865, 2024). "The expression level of CDK12 was generally upregulated in cancer cell lines of different tissue origins, which was consistent with the expression of CDK12 in 33 types of tumours analysed by the TCGA database." (PMID 38503865, 2024). "Moreover, we elucidated the mechanisms by which CDK12 helps tumours evade immune surveillance and proposed a new approach for developing CDK12-specific inhibitors." (PMID 38503865, 2024). "Noteworthy, PDO-33.3 displayed the lowest sensitivity to Lapatinib as single agent (IC50 = 1.3μM), suggesting that concomitant CDK12/13 inhibition may overcome an intrinsic resistance of this specific tumor to EGFR inhibition." (PMID 37202753, 2023). "CDK12 was previously reported to regulate MYC expression in other tumour context." (PMID 37599362, 2023). "While the expression levels of GRB7, MIEN1, ERBB2 and FBXL20 were considerably greater in tumour tissues than in normal tissues (p < 0.001 or p < 0.01), the expression levels of MED1 and CDK12 were significantly lower in tumour tissues than in normal tissues (p < 0.001)." (PMID 37525498, 2023). "In addition, a strong DNA damage increase was also detected in SR‐4835‐treated CRC cells and HCT116 subcutaneous tumours from either SR‐4835‐treatment or the CDK12‐knockdown group as reflected by the protein levels of γ‐H2AX." (PMID 36254394, 2022). "Here, we show that transgenic CDK12 overexpression in the mouse mammary gland per se is sufficient to drive the emergence of multiple and multifocal tumors, while, in cooperation with known oncogenes, it promotes earlier tumor onset and metastasis." (PMID 35550508, 2022). "In addition, breaks within known tumour suppressor genes CDK12, ZNF21 and RNF43 were observed and have been shown to result in loss in function." (PMID 35396535, 2022). "Given that CSCs undergo self‐renewal to facilitate tumour metastasis and recurrence, we wonder whether CDK12 inhibition affected traits of CSCs in CRC." (PMID 36254394, 2022). "Therefore, while CD44 and CDK12 likely represent only one of several cellular targets for each sdRNA, this study has redefined the CD44 and CDK12 tumor suppressive axes to include sdRNAs as potent regulators." (PMID 35455981, 2022). "Regardless, both CDK12-KI/PyMT and CDK12-KI/NeuN female mice displayed a higher propensity to develop multiple spontaneous lung metastases compared to control WT/PyMT and WT/NeuN mice sacrificed at the same endpoint (i.e., primary tumor size ~1.2 cm)." (PMID 35550508, 2022). "Tumor growth rates of A2780 CDK12 KO cells were slightly lower than A2780 cells." (PMID 35912188, 2022). "High CDK12 activity has been shown to accelerate tumor progression and treatment resistance." (PMID 34686673, 2021). "Tumor therapy might profit from our finding that not only CDK951 but also CDK12/13 inhibitor-mediated killing of cancer cells can be enhanced by cell-death-inducing cytokines and ligands." (PMID 34663829, 2021).
tumor (continued). "Moreover, most of these CDK12 mutations were mutually exclusive with alterations to the breast cancer type 1 and 2 susceptibility proteins (BRCA1 and BRCA2), a tissue-specific tumor suppressor, and a well-recognized DNA repair pathway component." (PMID 33805800, 2021). "Moreover, we examined the expression of JWA, CDK12, Ki67, and Caspase-3 in the tumor masses through IHC staining." (PMID 34686673, 2021). "Moreover, enhanced sensitivity to CDK12 has been found to influence tumor-specific (genetic or cellular) expression, such as MYC dependency, EWS/FLI rearrangement and PARP inhibition." (PMID 33805800, 2021). "Patients whose tumours exhibited no dMMR, CDK12 loss or PD-L1 expression also benefited from treatment in this trial." (PMID 33921181, 2021). "CDK12 promoted tumor progression by regulating c-myc/β-catenin pathway activation." (PMID 32489449, 2020). "There are ongoing clinical trials on patients with CDK12-aberrant tumours." (PMID 34316683, 2020). "Interestingly, CDK12 shows both tumorigenic and tumor-suppressive effects in different cancer types, which will be introduced in detail in the following." (PMID 32570740, 2020). "At the same time, a compensatory mechanism for the expression of CDK12-dependent HR genes (particularly BRCA1/2) in the tumour background must exist, and might even be essential for tumour onset and/or survival." (PMID 34316683, 2020). "Furthermore, we describe tumour-suppressive and oncogenic functions of CDK12 and its potential as a biomarker and inhibition target in anti-tumour treatments." (PMID 34316683, 2020). "Next, we tested if CDK12 induces tumor growth by activating PAK2-induced MAPK signaling pathway." (PMID 32483448, 2020). "CDK12 level was significantly higher in tumor tissues compared with adjacent tissues." (PMID 32483448, 2020). "Moreover, the overexpression of c-MYC, a central oncogene driving many tumours and super-enhancer-associated transcription factor genes, including RUNX1 and MYB, depends on CDK12." (PMID 34316683, 2020). "This suggests that the response of cancers with CDK12 aberrations to PARPi may be tumour type and context specific." (PMID 34316683, 2020). "Moreover, CDK12 inhibitors have the potential to be used to reverse resistance to PARPi in tumours with residual HR activity and to enhance the efficiency of existing DNA-damaging drugs, including widely used platinum-based chemotherapies." (PMID 34316683, 2020). "Moreover, we found that procaterol directly binds and inhibits kinase activity of CDK12, and suppresses cancer cell proliferation and tumor growth in vivo." (PMID 32483448, 2020). "The roles of CDK12 in the optimal transcription and translation of DNA replication genes and mitotic regulators, respectively, significantly contribute to the tumour-suppressive function of CDK12." (PMID 34316683, 2020). "High expression of CDK12 mRNA in tumor tissues was also detected in our study." (PMID 31523177, 2019). "In tumor tissues, high expression of CDK12 was identified in 43 cases (50%)." (PMID 31523177, 2019). "In tumor tissues with CDK12 high expression, a relatively high CD8+ cell density was found." (PMID 31523177, 2019). "The specific HRR mutations identified in the 21 tumour samples were: BRIP1 (n = 5), CDK12 (n = 3), RAD54L (n = 2), RAD51B (n = 2), RAD54L rearr (n = 1), ATM rearr (n = 1), FANCA rearr (n = 1), FANCD2 (n = 1), FANCL rearr (n = 1), FANCL (n = 1), RAD51C (n = 1), RAD52 del (n = 1), XRCC3 rearr (n = 1)." (PMID 30353044, 2018). "The mRNA levels of CDK12, PALB2 and XPF inversely associated with the in vivo DDP antitumor activity; higher CDK12 mRNA levels were associated with a higher recurrence rate in ovarian patients with low residual tumor." (PMID 29872499, 2018). "Is CDK12 a tumor suppressor or does it have oncogenic properties?" (PMID 29090014, 2017).
tumor (continued). "Finally, the CDK12 inhibitor dinaciclib in combination with the PARP1/2 inhibitor veliparib resulted in inhibition of tumor growth in vitro, in vivo and in a patient-derived xenograft model." (PMID 29090014, 2017). "Consequently, CDK12 can act as a tumor suppressor or its amplification can contribute to cancerogenesis depending on cellular context." (PMID 29090014, 2017). "Taken together, the dual role of CDK12 in cancerogenesis could be explained by the fact that CDK12 is essential for expression of both tumor suppressors and oncogenes, and it participates in multiple cellular processes." (PMID 29090014, 2017). "Importantly, combined treatment with PARP1/2 inhibitor veliparib and CDK12 inhibitor dinaciclib efficiently inhibited tumor growth in a patient-derived xenograft model." (PMID 29090014, 2017). "Considering these observations, CDK12 was suggested to be a tumor suppressor." (PMID 29090014, 2017). "This evidence represents only a small part of the abundant literature that attests the involvement of both CDK12/13 in different types of tumours, but well highlights the dual and sometimes opposite role played by them as oncogenes or tumour suppressors depending on the tumour context." (PMID 39533070, 2025). "Overall, CDK12 may have certain clinical value in the early diagnosis of these tumours." (PMID 38503865, 2024). "In this study, we have revealed the metabolic landscape of CRPC with CDK12 deficiency and shown that CDK12 deficiency enhances the energy metabolism of CRPC cells, including improving the TCA cycle and ETC activity, to sustain the growth and survival of tumour cells." (PMID 38736108, 2024). "Similarly, the highest scoring target mRNA identified for sdRNA-A24 (also containing two notable 3’UTR complementarities, one bearing 100% complementarity to sdRNA-A24 nucleotides 2 through 18) is a known tumor suppressor mutated in ~6% of patients with metastatic CRPC, CDK12 (bottom)." (PMID 35455981, 2022). "Using targeted next-generation sequencing analysis of tumor biopsies and germline DNA samples from mCRPC patients one study found that presence of deleterious DDR mutations in BRCA2, ATM, mismatch repair (MMR), and CDK12 genes was more frequent in patients with high tumor membranous PSMA expression." (PMID 34207069, 2021). "Moreover, the efficacy of THZ531 is currently being tested in an observational trial employing organoids derived from high grade serous ovarian cancer patients (NCT04555473), to verify whether CDK12 inhibition sensitises DDR‐proficient tumours to PARPi." (PMID 34092037, 2021). "Nonetheless, the presence of mutations in the DNA damage repair (DDR) genes (e.g., BRCA1, BRCA2, CDK12, ATM) has been associated with an increased number of DNA errors and high tumor neoantigen expression, and thus could be predictive of response to immune checkpoint monoclonal antibodies." (PMID 32911806, 2020). "Given that CDK12 maps to the smallest region of amplification of the HER2 amplicon, and recurrent fusions were identified in 13% (6/47) HER2-amplified tumours, we hypothesized that disruptions involving CDK12 were due to a copy number breakpoint within the amplicon." (PMID 24395524, 2014). "The transcriptional kinases CDK12 and CDK13 are central players in this process, but their influence is highly context-dependent, acting as oncogenic drivers in some tumors and tumor suppressors in others." (PMID 41491919, 2026). "As tumor cells frequently upregulate Bcl-2, inhibitors of CDK9 and CDK12/13 represent promising anticancer drugs." (PMID 42204137, 2026). "In contrast to their oncogenic roles, CDK12 and CDK13 can also function as tumor suppressors in specific contexts, particularly in ovarian and metastatic castration-resistant prostate cancers." (PMID 41491919, 2026).
tumor (continued). "Combining cyclin K/CDK12/CDK13 degrader, NCT02, with oxaliplatin and irinotecan exhibited synergistic anti-tumor effects in metastatic CRC cells." (PMID 41491919, 2026). "Notably, multiple linear regression analysis revealed that low pretreatment CDK12/13 expression (left) or high pretreatment STING activity signature expression (right) was independently associated with improved clinical outcomes, after adjusting for age, sex, and tumor site." (PMID 40955658, 2025). "Nevertheless, in line with the Cdk12/13 depletion data, YJ1206 treatment exhibited substantially stronger control of tumor growth in immunocompetent mice compared with immunodeficient mice." (PMID 40955658, 2025). "Most notably, the combination of CDK12 knockdown and TMZ led to complete tumor regression, with long-term survival in all mice." (PMID 40996961, 2025). "Here we have shown examples of recurrent in-frame fusion genes with the kinases CDK12 and MET as 3’ partners, fusions that have previously also been found in tumour samples." (PMID 41421967, 2025). "In summary, our study uncovers a pivotal role of CDK12-mediated phosphorylation in enhancing FOXA1’s transcriptional activity and tumor-promoting functions, thereby driving PCa progression." (PMID 41395253, 2025). "Our results define CDK12 as a key tumor suppressor in tubo-ovarian HGSC and highlight CDK13 targeting as a promising therapeutic approach in CDK12-inactive disease." (PMID 40504161, 2025). "Taken together, these results highlight the potent anti-tumor efficacy and improved safety profile of YJ1206, suggesting promising therapeutic potential as an orally bioavailable CDK12/13 degrader." (PMID 39353441, 2024). "The initiating event of the amplicon was due to a break in CDK12; followed by a duplication containing ERBB2 (chr17:37663478-38206775) shared by both BE and tumor, that generated the circular ecDNA through an episomal mechanism." (PMID 38744814, 2024). "To confirm the roles of BUD13, CDK12, and MBNL1 in tumor growth in vivo, we subcutaneously injected GBM BUD13(-) cells, CDK12(-) cells, MBNL1(+) cells, or a combination of the three cells to construct nude mice xenograft models." (PMID 36463205, 2022). "In silico and in vitro analyses revealed that two established PCa tumor suppressor genes, CD44 and CDK12, represent targets for sdRNA-D19b and sdRNA-A24, respectively." (PMID 35455981, 2022). "Pre-treatment of tumour-bearing mice with THZ1, a CDK7/CDK12/13 inhibitor, before infusion with CAR T-cells attenuated cytokine release by suppressing transcription of inflammatory genes, thus preventing the associated systemic toxicity." (PMID 35568739, 2022). "Meanwhile, on the TCGA portal, we found that CDK7, CDK8, CDK9, CDK12, CDK19, and CDK20 mRNA levels were differentially expressed in the 4 molecular tumor subtypes." (PMID 33686962, 2021).
tumor (continued). "We further performed western blotting to detect the protein expression of JWA, CDK12, Bcl-2, BAX, Caspase-3, and PCNA in xenograft tumor tissues." (PMID 34686673, 2021). "Taken together, CDK12 phosphorylates PAK2 at T134/T169 and activates MAPK signaling pathway speeding up cancer cell proliferation and tumor growth." (PMID 32483448, 2020). "CDK12 directly binds with and phosphorylates PAK2 at T134/T169, and thus activates MAPK signaling pathway that facilitates cell proliferation and tumor growth." (PMID 32483448, 2020). "Positive correlation was found between CDK12 expression score and number of CD8+ cells in tumor tissues (r=0.243, P=0.024)." (PMID 31523177, 2019). "Further, we have shown that in particular tumours, for PTEN, CDK12 and FAT4, this miRNA or methylation-based suppression happens independently of other gene regulatory factors, such as mutations and copy number changes." (PMID 30531873, 2018). "Further, across multiple cancer types, three key tumour suppressor genes, PTEN, FAT4 and CDK12, consistently tended towards exclusivity in their regulation, lending support for the importance of miRNA-based regulation of these genes." (PMID 30531873, 2018). "The selective CDK12 inhibitor SR-4835 effectively killed GBM cells, including resistant mesenchymal subtypes, at low concentrations, while sparing normal astrocytes, demonstrating tumor-specific toxicity." (PMID 40996961, 2025). "In vivo, CDK12 inhibition significantly extended survival without overt toxicity and induced complete tumor regression in a subset of animals." (PMID 40996961, 2025). "Indeed, overexpression of CDK12 in these tumours fuels the WNT and ErbB-PI3K signalling pathways, promoting the self-renewal of cancer stem cells and tumour progression." (PMID 39533070, 2025). "Interestingly, CDK12 ablation in CRPC contributes to the progression and the aggressive phenotype of the tumour by reprogramming the energy metabolism in favour of greater cell viability and drug resistance." (PMID 39533070, 2025). "Through the analysis of CDK12 expression and its correlation with TMB and precise radar chart analysis, it was observed that in seven types of tumours, namely, THYM, STAD, LUAD, LGG, SKCM, HNSC, and THCA, the expression level of CDK12 was significantly correlated with TMB." (PMID 38503865, 2024). "CDK12 phosphorylates PAK2, activating MAPK signaling and promoting tumor growth and cell division." (PMID 39769207, 2024). "The most common tumor types were ovarian (n = 23), breast (n = 15), pancreatic (n = 14), and prostate (n = 14); the most frequent enrollment genes were ATM (n = 38), BRCA1 (n = 28), BRCA2 (n = 15), SETD2 (n = 10), and CDK12 (n = 7)." (PMID 38710487, 2024). "Concerning copy number aberrations (CNAs), the top amplified genes in the samples from the primary tumor were ERBB2 (6/19, 32%), AURKA, PPM1D (4/19, 21%), and FGFR1 (3/19, 16%), while in the metastatic samples ERBB2 (7/17, 41%), CDK12, FGFR1 (4/17, 24%), and AURKA, MDM4, MYC (3/17, 18%)." (PMID 36717329, 2023). "Similarly, alterations in DNA damage response genes such as ATM, CDK12, and those of the RAD family (RAD51C, RAD54L) were observed across multiple tumour types." (PMID 37120671, 2023). "In numerous phase II and III clinical studies, little or no response to multiple PARPi was reported in diverse tumor types carrying HR mutations in genes such as CHEK2, ATM, FANCA, and CDK12." (PMID 37761329, 2023).